INS (insulin)
Diseases named in the same sentence as INS in open-access papers (continued):
Sharing a sentence is not in itself a finding about the gene and the disease.
Insulin resistance (continued). "We also observed a significant interaction effect between BCAA and insulin resistance, which revealed suppressed Ppargc1a expression in insulin-resistant cells treated with 20 mM BCAA versus insulin-resistant cells treated without additional BCAA." (PMID 39057712, 2024). "It is known that RAPA has been linked to an increased risk of developing new-onset T2D, likely due to a combination of insulin resistance and dysfunctional insulin secretion." (PMID 39201363, 2024). "Apparently, the formulas of HOMA-IR and HOMA-β, which contain fasting plasma glucose and insulin, can be valid and reliable in the prediction of insulin resistance." (PMID 39744182, 2024). "Studies show that during T2DM, the insulin signalling pathway is disturbed primarily due to chronic hyperglycaemia, which then contributes to pancreatic β-cell dysfunction and insulin resistance." (PMID 38791468, 2024). "The homeostasis model assessment of insulin resistance (HOMA-IR) index, widely used as an indirect method, is susceptible to variations in insulin measurement accuracy and lacks robust reproducibility." (PMID 39514584, 2024). "Severe fluctuations in blood glucose can lead to insulin resistance, which is characterized by a significant reduction in cellular sensitivity to insulin." (PMID 39796589, 2024). "Further, BMD(+) individuals had higher insulin and insulin resistance at baseline (Student’s t, p < 0.05), and higher blood glucose at both timepoints (Student’s t, p = 0.001)." (PMID 38706560, 2024). "Here, we also investigated the effects of β-cell GHSR deficiency under normal aging, accompanied by chronic low-grade inflammation, insulin resistance, and impaired insulin secretion." (PMID 38794702, 2024). "As HOMA-IR is reflective of hepatic insulin resistance, our data suggest the presence of liver insulin resistance and normal insulin action in myotubes in these three men with type 2 diabetes." (PMID 38814443, 2024). "Type 2 diabetes mellitus (T2DM), characterized by insulin resistance and declining insulin secretion, affects an estimated 537 million adults worldwide, with a projected increase of approximately 20% by 2030." (PMID 38790954, 2024). "For instance, valsartan has been shown to improve insulin resistance and enhance glucose-stimulated insulin secretion in patients with impaired fasting glucose or impaired glucose tolerance." (PMID 39337658, 2024). "We provide here novel evidence for a potent action of empagliflozin to increase vascular insulin sensitivity in persons with type 2 diabetes and insulin resistance." (PMID 38170166, 2024). "T2DM is a systemic inflammatory disease characterized by insulin resistance or reduced metabolic response to insulin in multiple tissues, including adipose tissue, liver, and skeletal muscle, and by reduced insulin synthesis in pancreatic β-cells." (PMID 38493114, 2024). "Adjuvant chemotherapy caused a worsened lipid profile (increased triglycerides, lower HDL levels), insulin resistance and increased plasma insulin levels that remained high during the first year after chemotherapy." (PMID 39415181, 2024). "The elevated levels of glucose, free fatty acids, and insulin can induce insulin resistance, which in turn can lead to an increase in triglycerides (TG) and a decrease in HDL cholesterol." (PMID 38726395, 2024). "Synthetically sulfated insulin was a type of formulation, believed to reduce antigenic responses in diabetic patients with immune insulin resistance." (PMID 39290144, 2024). "Insulin resistance refers to a physiological state in which the cells of the body exhibit diminished sensitivity to insulin, resulting in increased levels of glucose in the bloodstream." (PMID 39407506, 2024). "Fasting glucose, fasting insulin, and the insulin resistance measure homeostatic model assessment for insulin resistance (HOMA‐IR) were significantly decreased following CL treatment in aged mice." (PMID 39177077, 2024).
Insulin resistance (continued). "The insensitivity of hippocampal IRs and the reduced phosphorylation of insulin downstream signaling molecules are the hallmarks of hippocampus insulin resistance." (PMID 38987609, 2024). "FABP levels are positively associated with blood pressure, dyslipidemia, waist circumference, fasting insulin, and the homeostasis model assessment of insulin resistance index." (PMID 38731797, 2024). "HOMA-IR, usually considered a marker of hepatic insulin resistance, seemed to be stronger linked to levels of ADP compared to the Matsuda index, which is a better marker of peripheral insulin sensitivity." (PMID 39530118, 2024). "Insulin resistance should be suspected, especially in cases requiring high insulin doses or exhibiting features of insulin resistance such as acanthosis nigricans." (PMID 39108603, 2024). "This differs from data reported from the Western world where progression of T2D is described with an early development of insulin resistance, fully compensated by an increase in insulin secretion." (PMID 39049087, 2024). "Compared with control mice that were fed a low-fat diet (LFD), MetS mice that were fed HFD had increased bodyweight, fasting glucose, cholesterol, free fatty acid, insulin, and homeostatic model assessment for insulin resistance (HOMA-IR)." (PMID 39273569, 2024). "For the KEGG database, the affected pathways included insulin signaling pathway, insulin resistance, prolactin signaling pathway, estrogen signaling pathway, circadian rhythm, endocrine resistance, oxytocin signaling pathway, and MAPK signaling pathway." (PMID 39564184, 2024). "Insulin resistance, a key driver of various metabolic-related diseases, describes the reduced responsiveness of insulin-targeted tissues to elevated insulin levels." (PMID 39345890, 2024). "Monitoring of glucose-stimulated insulin release monitoring revealed heightened insulin secretion in BoNT/BTan mice compared to control BoNT/BCtl littermates, suggesting a beginning of insulin resistance." (PMID 39047908, 2024). "The pro-inflammatory cytokine, TNF-α, frequently assumes a pivotal role in the pathogenesis of hepatic steatosis and insulin resistance (IR), thereby impeding insulin secretion and impairing β-cell function." (PMID 38254542, 2024). "Post-surgical stress leads to insulin resistance, which manifests as a reduced responsiveness of target organs, tissues, or cells to the actions of insulin." (PMID 38411704, 2024). "Fundamental research indicates that excessive fat accumulation releases inflammatory cytokines and free fatty acids, disrupting insulin action and promoting insulin resistance." (PMID 39334176, 2024). "With adjustments, progression from Stage 1 to Stage 2 was positively related to insulin resistance, and inversely related to insulin sensitivity." (PMID 37914981, 2024). "Lastly, although efforts have been taken to ameliorate insulin resistance by using optogenetics to regulate insulin signaling or neuroendocrine activity, most of them lack long‐term experimental results and are absent of systemic therapeutic effects." (PMID 38751366, 2024). "We observed that the SIRD cluster (92.1%) exhibited a hyperinsulinemic phenotype characterised by low insulin sensitivity i.e. insulin resistance and high beta cell function, similar to the SIRD cluster." (PMID 39217248, 2024). "The presence of insulin resistance in patients with gestational diabetes mellitus (GDM) leads to an increase in maternal insulin demand." (PMID 39835257, 2024). "Previous studies have demonstrated that chronic low-grade inflammation induced by adipose tissue expansion and obesity leads to insulin resistance, impaired insulin secretion, and ultimately, hyperglycemia." (PMID 38388535, 2024). "These proteins have the ability to directly hinder insulin pathways, thus contributing to insulin resistance and obesity." (PMID 38317257, 2024).
Insulin resistance (continued). "Animal models have also demonstrated that hsa-miR-29b-3p’s contributes to insulin resistance and can inhibit insulin-stimulated glucose uptake, affecting blood glucose levels." (PMID 39176085, 2024). "Anti-inflammatory, anti-atherogenic and insulin-sensitizing properties make omentin-1 as a promising biomarker for future trials of tissue-specific insulin resistance." (PMID 39139157, 2024). "T2DM is a risk factor for various malignancies due to reduced pancreatic insulin secretion and insulin resistance, and it is also a known factor in tumor growth." (PMID 38468345, 2024). "Low levels of SYUA in humans are associated with insulin resistance, while an increase in SYUA is associated with increased adiposity, in addition to increased insulin sensitivity." (PMID 39595019, 2024). "Citric acid significantly reduces blood glucose levels and the insulin resistance index, while also enhancing insulin sensitivity." (PMID 38611548, 2024). "On the other hand, T2DM is a metabolic disease characterized by hyperglycemia, inadequate insulin release, insulin resistance, oxidative stress, and chronic inflammation, which can affect multiple organs and tissues." (PMID 39408723, 2024). "Leading to insulin resistance, visceral obesity, abnormal glucose tolerance.Impaired phosphorylation of insulin secondary Akt and muscle glucose uptake capacity.Better insulin sensitivity and glucose tolerance in mice fed diets with reduced POP concentrations." (PMID 38251002, 2024). "Participants were divided into groups based on their degree of insulin resistance using SSPG concentration tertiles: insulin sensitive (IS, SSPG ≤ 91 mg/dL), intermediate IR (IM, SSPG 92–199 mg/dL), and IR (SSPG ≥ 200 mg/dL)." (PMID 38672278, 2024). "Insufficient levels of BDNF can hinder the body’s glucose metabolism and insulin sensitivity, potentially contributing to the development of insulin resistance." (PMID 38773479, 2024). "The condition is considered a key precursor to the development of T2DM, as prolonged insulin resistance can lead to pancreatic β cell dysfunction and eventual failure to compensate for insulin resistance with increased insulin secretion." (PMID 38920999, 2024). "Although HbA1c% is almost identical between the two groups, fasting insulin levels and insulin resistance characterizing HOMA-IR, tend to increase in the patient group without reaching the level of significance." (PMID 39081789, 2024). "Although peripheral insulin resistance is found in almost all patients with T2D, the development of hyperglycemia and disease progression are actually attributable only to a defect in insulin secretion." (PMID 38942960, 2024). "Insulin resistance is therefore a common feature of sepsis, and insulin therapy improves sepsis outcomes." (PMID 39712009, 2024). "Insulin enhances muscle anabolism and inhibits muscle degradation, whereas shorter sleep duration induces insulin resistance through various metabolic pathways." (PMID 39008488, 2024). "Long-term AT ameliorates the pathophysiologic pathways involved in insulin resistance reducing adipokines, and inflammatory and oxidative stress responses leading to improved insulin sensitivity." (PMID 38494538, 2024). "T2DM is characterized by insulin resistance, impaired insulin secretion, and elevated glucose levels influenced by various organs and tissues." (PMID 38311623, 2024). "Type 2 diabetes (T2D) is a polygenic metabolic disorder characterized by insulin resistance in peripheral tissues and impaired insulin secretion by the pancreas." (PMID 38915897, 2024). "Insulin resistance is characterized by reduced cellular responsiveness to insulin, leading to elevated insulin secretion and fasting blood glucose levels." (PMID 39770957, 2024). "Cell mass, especially β-cell mass, can expand during adulthood in response to increased body weight and insulin resistance, thereby displaying an ability to adapt to the increased insulin demand." (PMID 38414818, 2024).
Insulin resistance (continued). "This leads to a decrease in insulin resistance and an increase in the sensitivity of these cells to insulin." (PMID 38195613, 2024). "SUCNR1, expressed in β cells and upregulated in hyperglycemia, is essential for maintaining insulin secretion in diet-induced insulin resistance and prediabetic states." (PMID 38713514, 2024). "Insulin resistance significantly reduces SNCA expression in insulin-resistant C2C12 myoblast and skeletal muscle tissues of type 2 diabetic mice." (PMID 39594624, 2024). "Fascinatingly, amyloid-beta adheres and impedes the binding of insulin-to-insulin receptors (IRs), thus exacerbating insulin resistance." (PMID 39596378, 2024). "Hepatic insulin resistance induces higher fasting glucose levels due to the decreased insulin-mediated suppression of hepatic glucose production." (PMID 39769002, 2024). "HFD-fed mice showed increased body weight, a tendency for increased fasting glycemia and plasma insulin concentrations, reduced glucose tolerance, and increased insulin resistance, when compared to controls." (PMID 37794263, 2024). "Our emerging results showed significantly decreased levels of trimethylamine N-oxide (TMAO) with progression from insulin sensitivity to insulin resistance and T2D." (PMID 39195553, 2024). "correlated positively with flavone and flavonol biosynthesis and negatively with insulin levels and insulin resistance." (PMID 38612453, 2024). "The increased production of free radicals and ROS and impairment of endogenous antioxidants can impair insulin signaling pathways and contribute to insulin resistance." (PMID 38893645, 2024). "Homeostatic model assessment 2 (HOMA2) is a non-invasive, commonly used mathematical model for estimating beta-cell function (-B), insulin sensitivity (-S), and insulin resistance (-IR)." (PMID 38510703, 2024). "During bed rest, plasma fasting insulin concentration increased significantly, indicating the development of inactivity-induced insulin resistance." (PMID 39765759, 2024). "Insulin needs are unmet because of obesity-induced insulin resistance, and obesity influences the progression of islet autoimmunity." (PMID 39099754, 2024). "Obesity causes macrophages to release inflammatory cytokines that inhibit insulin sensitivity, and simultaneously enable immune cells to reside within adipose tissue, resulting in inflammation in these tissues, thereby promoting insulin resistance." (PMID 38274329, 2024). "Following the increase in body mass, the baseline insulin concentrations, insulin secretion, and insulin resistance were observed to increase, while insulin clearance decreased." (PMID 38392975, 2024). "Insulin resistance and the resulting compensatory increase in plasma insulin levels activate mechanisms that enhance renal sodium reabsorption and stimulate sympathetic nervous system activity." (PMID 39204141, 2024). "In our experiment, the high-fructose diet induced insulin resistance in mice, as evidenced by higher serum insulin concentrations in the DC group (9.75 ± 0.43 mIU/L) than in the NC group (7.77 ± 0.54 mIU/L) (p < 0.0001)." (PMID 39063287, 2024). "T2D is a chronic and progressive disease characterized by insulin resistance and/or insufficient insulin secretion resulting from β-cell dysfunction and decreases in β-cell mass." (PMID 38514666, 2024). "Adipose tissue macrophages are key factors in obesity-induced insulin resistance by regulating a series of insulin-related and inflammatory-factor-related signaling pathways through paracrine interactions between adipocytes and macrophages." (PMID 39200288, 2024). "Elderly women often exhibit a loss of the protective effects of estrogen on the cardiovascular system and insulin sensitivity, leading to a higher likelihood of dyslipidemia, endothelial dysfunction, and insulin resistance." (PMID 39588335, 2024).
Insulin resistance (continued). "The effects resulted in improved intake and digestibility of nutrients, accompanied by changes in the responses to serum glucose, insulin, albumin, and cholesterol, indicating improved glucose tolerance and reduced insulin resistance." (PMID 39682453, 2024). "Fasting blood glucose is elevated due to insulin resistance or a relative decrease in insulin secretion." (PMID 39315007, 2024). "Insulin, C-peptide, and markers of β cell autoimmunity were within normal range, suggesting insulin resistance." (PMID 38775154, 2024). "The hyperinsulinemic–euglycemic clamp (HEC) is the gold standard in assessing the insulin sensitivity of peripheral tissues, and the homeostatic model assessment for insulin resistance (HOMA-IR) is a widely used method." (PMID 38476671, 2024). "Insulin resistance (IR) refers to the diminished sensitivity or impaired response of target organs or tissues to insulin, which culminates in the compromised uptake and utilization of glucose." (PMID 38702735, 2024). "Insulin resistance is a pathologic condition in which adipocytes, hepatocytes, and skeletal muscle cells, insulin‐dependent cells, fail to respond appropriately to physiological circulating insulin levels." (PMID 38953241, 2024). "In the state of obesity, the target cells of insulin can activate inflammatory pathways, leading to insulin resistance." (PMID 39758340, 2024). "Insulin resistance is a condition where the body can produce insulin, but cells cannot efficiently utilize it." (PMID 39606781, 2024). "Insulin resistance can be characterized as the insufficient reaction of target tissues to insulin stimulation." (PMID 38425702, 2024). "Generally, we can understand that type 2 DM results from increased insulin resistance, closely related to poor lifestyle habits, interfering with insulin function." (PMID 38304078, 2024). "This condition is associated with a gradual decline in the ability to produce and release insulin, frequently on the background of insulin resistance." (PMID 38257166, 2024). "Insulin resistance refers to the impaired responsiveness of tissues, such as muscles, fat, and liver, to insulin at its average concentration." (PMID 38805166, 2024). "Gestational diabetes mellitus (GDM) is a common condition in women with pre-existing obesity and insulin resistance as well as insulin secretion defects, typically diagnosed by week 26 of pregnancy." (PMID 39065137, 2024). "Similarly, the consumption of liquid and simple carbohydrates, such as sugar-sweetened beverages, can lead to a rapid increase in insulin and glucose levels in the bloodstream, which may contribute to the development of insulin resistance and further increase the risk of NAFLD." (PMID 39300472, 2024). "In contrast with the model and the HFHS + MilliQ groups, two treated animal groups showed dose-dependent improvements in all of the investigated mentioned biochemical variables including serum glucose, insulin, and insulin resistance." (PMID 38961451, 2024). "Typically, patients with periodontitis exhibit increased levels of the inflammatory mediator tumor necrosis factor (TNF)-alpha, which interferes with insulin signal transmission, thereby promoting insulin resistance." (PMID 39563204, 2024). "Overexpression of Angptl7 in healthy mice can also lead to insulin resistance-like characteristics, resulting in inhibited glucose uptake and insulin signal pathway." (PMID 38714962, 2024). "The Homeostasis Model Assessment of Insulin Resistance (HOMA-IR) represents a diagnostic tool used in clinical settings to evaluate the resistance of insulin, calculated as HOMA-IR = (Fasting Insulin (mU/L) × Fasting Glucose (mmol/L))/22.5." (PMID 39203828, 2024). "Deleting CEACAM1 exclusively in hepatocytes (as in AlbCre+Cc1fl/fl mice) impaired hepatic insulin clearance at 2–3 months of age, followed by hyperinsulinemia-driven hepatic insulin resistance and steatosis at ~6 months of age." (PMID 39640841, 2024).